SP100 (SP100 nuclear body protein)
Description:
Together with PML, this tumor suppressor is a major constituent of the PML bodies, a subnuclear organelle involved in a large number of physiological processes including cell growth, differentiation and apoptosis. Functions as a transcriptional coactivator of ETS1 and ETS2 according to PubMed:11909962. Under certain conditions, it may also act as a corepressor of ETS1 preventing its binding to DNA according to PubMed:15247905. Through the regulation of ETS1 it may play a role in angiogenesis, controlling endothelial cell motility and invasion. Through interaction with the MRN complex it may be involved in the regulation of telomeres lengthening. Also plays a role in infection by viruses, including human cytomegalovirus and Epstein-Barr virus, through mechanisms that may involve chromatin and/or transcriptional regulation.
Synonyms: lysp100b
Tractability: Small molecule: a structure with a bound ligand is known. PROTAC: UniProt records ubiquitination sites on it; ubiquitination databases record sites on it; its protein half-life has been measured.
Gene: Protein-coding gene on chromosome 2 (230,415,942 to 230,545,606, forward strand). Ensembl gene ENSG00000067066.
Subcellular location: Nucleus; Nucleus, PML body; Nucleus, nuclear body; Cytoplasm; Nucleus (Isoform Sp100-C)
Subcellular location (Human Protein Atlas): Nuclear bodies; Nucleoplasm
Pathways (Reactome):
Immune System: Interferon gamma signaling
Metabolism of proteins: SUMOylation of DNA damage response and repair proteins
Gene Ontology:
Molecular function: chromo shadow domain binding; DNA-binding transcription factor activity, RNA polymerase II-specific; identical protein binding; kinase binding; protein binding; protein dimerization activity; protein domain specific binding; transcription corepressor activity; DNA binding
Biological process: maintenance of protein location; negative regulation of endothelial cell migration; negative regulation of protein export from nucleus; negative regulation of transcription by RNA polymerase II; positive regulation of transcription by RNA polymerase II; regulation of angiogenesis; regulation of extrinsic apoptotic signaling pathway via death domain receptors; regulation of Fas signaling pathway; response to type I interferon; response to type II interferon; telomere maintenance; regulation of transcription by RNA polymerase II; type I interferon-mediated signaling pathway; type II interferon-mediated signaling pathway; defense response; DNA metabolic process; immune response; regulation of viral process
Cellular component: chromosome, telomeric region; cytoplasm; Mre11 complex; nuclear body; nucleoplasm; nucleus; PML body
Genetic constraint (gnomAD): Loss-of-function variants: 44 observed, 69.58 expected, observed/expected ratio (o/e) 0.63, 90% interval 0.5 to 0.81. The upper end of that interval is the gene's LOEUF score, 0.81, which puts it in group 3 of 6, group 1 being the genes least tolerant of losing a copy. Missense variants: 628 observed, 724.56 expected, observed/expected ratio (o/e) 0.87, 90% interval 0.81 to 0.93. Synonymous variants: 208 observed, 249.81 expected, observed/expected ratio (o/e) 0.83, 90% interval 0.74 to 0.93.
Homologues: Orthologues: chimpanzee SP100 (99% identical), macaque SP100 (69% identical), dog SP100 (57% identical), zebrafish ubtf (10% identical), zebrafish ubtfl (9% identical), Caenorhabditis elegans hmg-3 (8% identical), Caenorhabditis elegans hmg-4 (7% identical). Paralogues in human: SP140L (38% identical), SP140 (38% identical), SP110 (27% identical), UBTF (11% identical), TOX3 (9% identical), TOX2 (9% identical), TOX4 (9% identical), SSRP1 (8% identical), HMGXB4 (8% identical), TOX (8% identical), SMARCE1 (6% identical), HMGB2 (5% identical), and 8 more.
Diseases named in the same sentence as SP100 in open-access papers:
SP100 is named in the same sentence as 57 diseases in open-access papers, as found by Europe PMC text mining. Sharing a sentence is not in itself a finding about the gene and the disease. The quoted sentences say what the papers report.
primary biliary cholangitis (18 papers, 2009 to 2025). Primary biliary cholangitis (PBC) is a chronic and slowly progressive cholestatic liver disease of autoimmune etiology characterized by injury of the intrahepatic bile ducts that may eventually lead to liver failure. "Speckled 100 kDa (SP100) is a nuclear protein that was discovered in association with promyelocytic leukemia nuclear bodies (PML-NBs) in patients with primary biliary cirrhosis." (PMID 34298819, 2021). "Antibodies directed against PML and Sp100 are associated with primary biliary cholangitis (PBC) and the presence of these antibodies assists in the diagnosis of patients who are anti-mitochondrial antibody (AMA)-negative." (PMID 32776893, 2020). "The multiple nuclear dots pattern (AC-6) is associated with anti-Sp100, anti-MJ/NXP-2, and anti-PML, being useful in the diagnosis of diseases such as primary biliary cholangitis and autoimmune myopathy." (PMID 38283335, 2023). "Out of 97 patients, 19 were positive for AMA, 4 for anti-Sp100, 1 for anti-Gp210 and 7 were diagnosed with primary biliary cholangitis." (PMID 35207242, 2022). "These included anti-complement 3 (lupus), anti-complement C1q (lupus), anti-SP100 (lupus), PR-3 (vasculitis), anti-LC-1 (autoimmune hepatitis), anti-Nup62 (primary biliary cirrhosis), anti-MI-2 (myositis), and anti-vimentin (rheumatoid arthritis)." (PMID 33897700, 2021). "The diagnostic value of antinuclear antibodies (ANAs) including anti-gp210 and anti-sp100 for primary biliary cholangitis/cirrhosis (PBC) has been widely reported." (PMID 31281353, 2019). "In conclusion, our results show that SP140L is phylogenetically recent member of SP100 proteins and acts as an autoantigen in primary biliary cirrhosis patients." (PMID 26347895, 2015). "The Sp100 protein was the first ND10 constituent identified using sera of patients suffering from the autoimmune disease primary biliary cirrhosis (PBC)." (PMID 21994592, 2009). "Similar to SP100, the SP140 and SP140L proteins are autoantigens in primary biliary cirrhosis, and SP140 is active in chronic lymphocytic leukemia." (PMID 34298819, 2021). "Primary biliary cholangitis (PBC) is a cholestatic, autoimmune liver disease, characterized by the existence of anti-mitochondrial (AMA) and antinuclear antibodies like anti-gp210 and anti-Sp100 in the patients’ sera." (PMID 39844835, 2024). "In addition, SP100 and SP140 are autoantigenic targets in primary biliary cirrhosis (PBC), a slowly progressing autoimmune disease that destroys primarily the bile canaliculi and leads to cholestasis." (PMID 26347895, 2015). "Similarly to SP100 and SP140 protein, we detected serum autoantibodies to SP140L in patients with primary biliary cirrhosis using luciferase immunoprecipitation system and immunoblotting assays." (PMID 26347895, 2015). "The proof of negative AMA and PBC-specific ANA (sp100, gp210) may help to exclude primary biliary cholangitis." (PMID 33377990, 2021).
viral infection (14 papers, 2011 to 2025). "Automated quantitation of PML NBs using immunofluorescence staining of PML and SP100 proteins revealed that the resistant ATRX-deficient/ALT cell lines contain more PML NBs than cell lines that were sensitive to mutant virus infection." (PMID 30745338, 2019). "It should be noted that although cytosolic Sp100 constitutes a previously neglected portion of the whole-cell level in HEp-2 cells, the nuclear translocation of cytosolic Sp100 (Cyto-Sp100) during virus infection was clear and prominent." (PMID 36383022, 2022). "The enhancement of virus infection with Sp100 knockdown was much more pronounced at lower MOIs as has been previously reported, possibly explained by efficient viral antagonism of Sp100 at higher MOI." (PMID 30122656, 2018). "Upon entry into cells, human papillomaviruses (HPV) encounter anti-viral nuclear bodies, called ND10, and components of these bodies, such as Sp100, restrict early viral infection." (PMID 28968443, 2017). "Most likely, Sp100 attempts to restrict late viral infection, but HPV antagonizes this process, and probably hijacks some of its functions." (PMID 28968443, 2017). "They revealed that PML and DAXX knock-down leads to a reduction in HPV18 transcription, while SP100 behaves as a repressor of viral infection." (PMID 26148509, 2015). "Significantly, in the context of viral infection response, four prominent isoforms of SP100 (namely SP100A, SP100B, SP100C, and SP100HMG) have been discerned, prompting us to undertake a comparative analysis of the expression levels exhibited by these transcripts." (PMID 38118002, 2024). "Papillomavirus E6 and E7 proteins were suggested to enable viral genome replication, Brd4 can enhance replication by concentrating viral processes in specific regions of the host nucleus, and the contribution of Sp100 in regulating the viral infection can be further investigated." (PMID 37376685, 2023). "Notably, the expressions of PML-NB components such as PML and SP100 themselves are also induced by the interferon pathway, corroborating their crucial role in the intrinsic immunity to viral infection." (PMID 29065450, 2017). "Daxx and Sp100, important components of PML-nuclear bodies, were also upregulated both directly by BoIFN-γand indirectly by viral infection." (PMID 36016774, 2022). "Several PML-NB components like PML itself, SP100, DAXX, and ATRX are bona fide restriction factors for viral infection, undermined by the observation that PML-NB components like PML, Sp100, and DAXX are induced by interferon." (PMID 31500286, 2019). "Interferon signalling is essential for the production of anti-viral mediators (such as OAS1, Mx1, SP100, and TRIM22) to defend against virus infection." (PMID 28273165, 2017). "PML-NB components PML, SP100, DAXX and ATRX are bona fide restriction factors for viral infection and members of different virus families have evolved sophisticated mechanisms to bypass PML-NB-mediated immunity." (PMID 29065450, 2017). "Several ND10 components, like PML, Sp100, Daxx and ATRX have been shown to be part of a cellular defense mechanism against viral infection and therefore became targets of viral effector proteins." (PMID 24453968, 2014). "The most important ND10 proteins include SP100, Daxx, and PML, all of which have been demonstrated to be intrinsic defense mechanisms against viral infection." (PMID 21552525, 2011). "The inhibitory effects of ND10 proteins on viral infection have been demonstrated on PML, Daxx, and SP100." (PMID 21552525, 2011). "However, Sp100 proteins have potent pro-viral and anti-viral responses and thus the NIKS Sp100 KO cells will be valuable for the study of viral infection of keratinocytes in monolayer culture or in a stratified epithelium." (PMID 40568077, 2025).
viral infection (continued). "In this follow up study, we show that Sp100 does not substantially regulate viral infection in the maintenance phase, however at late stages of infection Sp100 interacts with amplifying viral genomes to repress viral processes." (PMID 28968443, 2017). "Although a great deal of evidence supports the theory that ND10 components such as PML, Daxx, and SP100 are viral gene repressors and protect host cells against many viruses, the effects of the ND10 structure on viral infection have been not determined." (PMID 21552525, 2011).
promyelocytic leukemia (10 papers, 2013 to 2024). "In cancer, SP family proteins, such as SP100, have been associated with malignancies like acute promyelocytic leukemia (APL) and breast cancer." (PMID 38468469, 2024). "NURD displays homology to the protein SP100, a component of the promyelocytic leukemia-associated nuclear body, implying that NUP98 might be involved in the regulation of nuclear bodies and is consistent with the reported link of NUP98 to leukemia." (PMID 23468646, 2013). "SP100 is a type of nuclear antigen which encodes a subnuclear organelle and is major component of the PML- (promyelocytic leukemia-) SP100 nuclear bodies." (PMID 35971449, 2022). "Sp100 isoforms are resident component proteins of promyelocytic leukemia-nuclear bodies (PML-NBs), dynamic nuclear sub-structures which regulate host immune defenses against many pathogens." (PMID 33598438, 2020). "Bright (B-cell regulator of IgH transcription) interacts with Sp100, which is a component of promyelocytic leukemia (PML) nuclear bodies and the lymphoid restricted homolog of Sp100, LYSp100/Sp140." (PMID 33409278, 2020). "The ‘speckled’ nuclear distribution of Sp100 predominantly colocalizes with promyelocytic leukemia-nuclear bodies (PML-NBs)." (PMID 33598438, 2020). "The promyelocytic leukemia-SP100 nuclear bodies (family V), which harbor a PHD-BRD tandem reader cassette are a notable exception and some families are still insufficiently covered, including members of families VI and VII, which also have atypical and shallow Kac-binding pockets." (PMID 31015424, 2019). "Sp100 is a nuclear protein with an unknown function, co-localised in nuclear dots with PML, which is a transformation and cell growth suppressing protein expressed in promyelocytic leukemia cells." (PMID 35328252, 2022).
breast carcinoma (6 papers, 2020 to 2024). "Mutation of SP100 appeared to be linked to a family history of breast cancer in PAAD patients." (PMID 37354211, 2023). "More specifically, after silencing the CLOCK gene, the genes primarily involved in breast cancer progression included CCL5, SP100, and BDKRB2." (PMID 39587706, 2024). "Notably, SP100 is responsible for the formation of PML nuclear bodies, predominantly serving as a suppressor of tumorigenesis across various cancer types, encompassing melanoma, glioblastoma, leiomyosarcoma, breast cancer, and laryngeal cancer." (PMID 38118002, 2024). "Moreover, the expression of SP100 could regulate the transcriptional activity of ETS1 and further influence the cell invasion in breast cancer." (PMID 32431729, 2020).
Cirrhosis (6 papers, 2019 to 2025). A chronic disorder of the liver in which liver tissue becomes scarred and is partially replaced by regenerative nodules and fibrotic tissue resulting in loss of liver function. "Among ANAs, anti-gp210 and anti-sp100 have emerged as highly specific and prognostically relevant biomarkers, with anti-gp210 strongly associated with cirrhosis, hepatic failure, and increased mortality." (PMID 41375805, 2025). "Consistent with our study, relevant studies indicated that the anti‐sp100‐positive patients with PBC who had an increased frequency of DRB1*03:01 suffered from cirrhosis more frequently compared to anti‐sp100‐negative patients." (PMID 39099389, 2024).
HCMV infection (6 papers, 2018 to 2023). "The role of immunity factors restricting HCMV infection, with Sp100 as PML-NB component, has been reviewed elsewhere." (PMID 33598438, 2020). "In accordance with this immunofluorescence experiment, protein levels, as measured on western blots, of PML itself and of the PML NB components Sp100 and Daxx, decreased after HCMV infection, but increased after KSHV infection of primary endothelial cells." (PMID 31059555, 2019). "The enhancement of HCMV infection was confirmed using five independently derived CRISPR/Cas9 knockdown lines for both Sp100 and HLTF." (PMID 30122656, 2018). "The PML-NB protein Sp100 acts to restrict HCMV infection and was thus selected as a positive control." (PMID 30122656, 2018). "The effect of Sp100 on HCMV infection was assessed similarly." (PMID 37058447, 2023). "IE1 co-transfection with each Sp100 isoform was shown to reduce their SUMOylation; this effect is especially evident for Sp100A, but unSUMOylated Sp100A levels also decrease at later times post HCMV infection." (PMID 33598438, 2020). "Among these candidates, five host factors (PML, Sp100, ISG15, IRP9, and RSAD2) have been related to HCMV infection and were further investigated." (PMID 37058447, 2023). "In cells permissive to HCMV infection, PML and Sp100 act as cellular restriction factors by inhibiting viral IE gene expression." (PMID 37058447, 2023). "The impact of PML-NBs on lytic HCMV infection has been characterized by numerous studies in primary human fibroblasts, which revealed an inhibitory effect of the main NB components PML, Sp100, Daxx and ATRX on viral immediate–early (IE) gene expression." (PMID 36233232, 2022). "HLTF thus acts to restrict significantly the efficiency with which a low MOI HCMV infection activates immediate-early gene expression, with an efficiency similar to that of the recognized HCMV restriction factor Sp100." (PMID 30122656, 2018). "Notably, this group contained the known HCMV restriction factors Sp100, MORC3, DAXX, and HLTF in addition to cell cycle regulating protein ANAPC1, all of which have been reported to be degraded during HCMV infection by ourselves and others." (PMID 33585265, 2020). "As opposed to Sp100 merely being used as a PML-NB marker assumed to behave as PML, this section focuses on Sp100 isoforms during HCMV infection." (PMID 33598438, 2020).
glioma (5 papers, 2020 to 2024). A benign or malignant brain and spinal cord tumor that arises from glial cells (astrocytes, oligodendrocytes, ependymal cells). "Similar suppression of viral gene expression was observed in glioma cells with elevated PML or Sp100 levels in this study." (PMID 37058447, 2023). "We found that PML-NB dots in SOX2-OE cells were much fewer in number and smaller in size than those in Ctl cells, arguing that SOX2-induced downregulation of PML and Sp100 disrupts PML-NBs formation in glioma cells." (PMID 37058447, 2023). "The mRNA expression of APOBEC3C, FCGRT, GNG5, and SP100 was elevated in glioma, whereas the expression of ADAP2, ALOX5AP, and LRRC25 was low." (PMID 32431729, 2020). "Regarding the role of SP100 in glioma, previous study revealed that SP100 was overexpressed in glioblastoma cells and involved in the regulation of glioblastoma cell proliferation and migration." (PMID 32431729, 2020). "Gene changes, prognostic model, and function assessment of SP100 gene families in glioma." (PMID 38468469, 2024). "SP100 was first identified as a nuclear autoimmune antigen and is a constituent of the nuclear body, serving as an important tumor suppressor in diverse cancers, including pancreatic cancer, leukemia and glioma." (PMID 38118002, 2024). "Together these studies demonstrated that SOX2 downregulates PML and Sp100 in gliomas." (PMID 37058447, 2023). "In previous studies, the inducing overexpression of SP100 reduced the proliferation and migration of glioblastoma tumor cells, which indicated that SP100 might be a promising target for glioma." (PMID 36676646, 2022). "In addition, downregulation of PML and Sp100 was observed in glioma samples." (PMID 37058447, 2023). "Due to the SOX2-mediated downregulation of PML and Sp100, the PML-NBs formation is greatly reduced in glioma cells, removing the restriction on HCMV gene expression." (PMID 37058447, 2023). "Our studies demonstrated that SOX2 downregulated promyelocytic leukemia (PML) and Sp100 and consequently facilitated viral gene expression by decreasing the amount of PML nuclear bodies in HCMV-infected glioma cells." (PMID 37058447, 2023). "SP100 and SP140 showed a higher expression in the glioma tissue than in normal tissue." (PMID 38468469, 2024). "This assay showed that SOX2-OE inhibited the promoter activity of PML but not Sp100 in 293T and glioma cells." (PMID 37058447, 2023). "Additionally, in gliomas, SOX2 can lead to a worse prognosis by downregulating PML and SP100." (PMID 38468469, 2024). "However, we did not observe significant changes in PML and Sp100 expression in HCMV-infected glioma cells." (PMID 37058447, 2023).